MLKL (mixed lineage kinase domain like pseudokinase)
Diseases named in the same sentence as MLKL in open-access papers (continued):
Sharing a sentence is not in itself a finding about the gene and the disease.
Psoriasiform dermatitis (1 paper, 2021). A skin abnormality characterized by redness and irritation, with thick, red skin that displays flaky, silver-white patches (scales). "Inhibition of RIPK1 or MLKL could attenuate necroptosis both in vitro and in vivo, and powerfully reduce inflammation in psoriasiform dermatitis mice induced by IMQ." (PMID 34977874, 2021). "Inhibition of RIPK1 or MLKL could reduce inflammation of psoriasiform dermatitis in mice." (PMID 34977874, 2021).
rectal tumors (1 paper, 2022). "Necroptosis protein expression was also evaluated by measurement of MLKL protein levels in the mucinous and non-mucinous rectal tumors." (PMID 35912268, 2022).
reovirus infection (1 paper, 2022). "Necroptosis, another form of cell death described to be induced by reovirus infection, was also studied by investigating the phosphorylation of the pseudokinase mixed lineage kinase domain-like (MLKL)." (PMID 35869278, 2022). "No induction of MLKL phosphorylation was observed in hPS1 fibroblast upon reovirus infection or stimulation with the necroptosis-inducing mixture TBZ." (PMID 35869278, 2022).
respiratory syncytial virus infection (1 paper, 2023). "Furthermore, recent studies confirm that p-MLKL-mediated macrophage necroptosis leads to the pathogenesis of respiratory syncytial virus infection, NASH, and inflammatory arthritis." (PMID 36859525, 2023).
RSV bronchiolitis (1 paper, 2022). "As the inhibition of MLKL or targeting of HMGB1/RAGE pathway attenuates the release of pro-inflammatory HMGB1 and decreases viral load, this suggests that the pharmacological targeting of these pathways may be of benefit for the treatment of severe RSV bronchiolitis." (PMID 35712662, 2022).
SARS-CoV infection (1 paper, 2023). "Recent reports showed that both Caspase-8–mediated apoptosis and MLKL-driven necroptosis contribute to disease severity following SARS-CoV infection." (PMID 37494451, 2023).
selenium deficiency (1 paper, 2023). A nutritional deficiency disease resulting from inadequate selenium levels in the body, which can lead to impaired function of selenoproteins essential for antioxidant defense and thyroid hormone metabolism. "The high level of expression of c-FLIP, MLKL, RIPK1, and RIPK3 indicated that necroptosis also causes lung damage during selenium deficiency." (PMID 37107171, 2023).
temporal lobe epilepsy (1 paper, 2025). A localization-related (focal) form of epilepsy characterized by recurrent seizures that arise from foci within the temporal lobe, most commonly from its mesial aspect. "KEY POINTS: In the early stage of experimental temporal lobe epilepsy with hippocampal sclerosis (TLE-HS), we observed activation of RIPK1, RIPK3 and MLKL in CA1 astrocytes, along with a reduction in astrocyte density, providing evidence for necroptotic cell death." (PMID 40629542, 2025).
Testicular atrophy (1 paper, 2024). Wasting (atrophy) of the testicle (the male gonad) manifested by a decrease in size and potentially by a loss of fertility. "The precise role of necroptosis in the testes has been debated, with support for and against the involvement of the terminal cell death effector, MLKL, in driving testicular atrophy." (PMID 39572538, 2024).
thymic lymphoma (1 paper, 2022). "Additionally, we directly examined whether the expression of MLKL was reduced in thymic lymphoma cells." (PMID 36161785, 2022).
toxic epidermal necrolysis (1 paper, 2018). Toxic epidermal necrolysis (TEN) is an acute and severe skin disease with clinical and histological features characterized by the destruction and detachment of the skin epithelium and mucous membranes. "We also reported that dabrafenib is a potential therapeutic agent for toxic epidermal necrolysis (TEN) via the inhibition of RIP3-mediated MLKL phosphorylation-induced necroptosis." (PMID 30237400, 2018).
triple-negative breast carcinoma (1 paper, 2025). An invasive breast carcinoma which is negative for expression of estrogen receptor (ER), progesterone receptor (PR), and human epidermal growth factor receptor 2 (HER2). "For example, a combination of SHK and Chi-Ag NPs is able to induce effective ICD in triple-negative breast cancer tissues by synergistically inducing tumor cell necroptosis through the upregulation of RIPK3, pRIPK3, and tetrameric MLKL expression." (PMID 40305291, 2025).
type-1 diabetes (1 paper, 2022). "We then induced type-1 diabetes in MLKL-knockout and wild-type mice by injection of STZ." (PMID 36030201, 2022). "In a mouse model of STZ-induced type-1 diabetes, the levels of phosphorylated RIPK3 and MLKL protein were higher in diabetic hearts after 2 months of last STZ injection when compared to sham mice." (PMID 36030201, 2022). "Type 1 diabetes was induced in RIPK3 knockout, MLKL knockout and wild-type mice." (PMID 36030201, 2022).
vitiligo (1 paper, 2025). Generalized well circumscribed patches of leukoderma that are generally distributed over symmetric body locations and is due to autoimmune destruction of melanocytes. "Necroptosis has been strongly linked to vitiligo, as melanocytes from perilesional skin affected by vitiligo show significant augmented phosphorylated receptor-interacting protein kinase 3 (RIP3) and phosphorylated mixed lineage kinase domain-like protein (MLKL), both key markers of necroptosis." (PMID 41007740, 2025).
Yersinia infection (1 paper, 2024). "RIPK3/MLKL-induced programmed necrosis also activates NLRP3, presumably via potassium efflux, thereby providing another route to caspase-1 engagement during Yersinia infection, even when caspase-8 cannot be activated." (PMID 39058785, 2024). "Moreover, neither RIPK3 nor MLKL undergoes phosphorylation in WT cells during Yersinia infection or IKK blockade, suggesting that necroptosis is not activated by Yersinia when caspase-8 is present and functional." (PMID 39058785, 2024).
tumor (202 papers, 2014 to 2026). "Phosphorylation of MLKL leads to necroptosis, causing the cell membrane to become permeable and releasing damage-associated molecular patterns (DAMPs) that alter the tumor microenvironment." (PMID 41584509, 2025). "CRISPR-based mechanistic studies of necrosome components RIPK3 and MLKL in T-cell lymphoma models demonstrate that loss of these proteins substantially impairs tumor cell response to toltrazuril." (PMID 41267084, 2025). "In pancreatic cancer, elevated RIPK1 and RIPK3 levels enhance tumor migration and invasion, while low MLKL expression is associated with worse outcomes." (PMID 40969770, 2025). "Using miRNA encoding necroptosis mediator MLKL to treat melanoma cells not only induces necroptosis but also elicits robust antitumor responses, significantly enhancing tumor growth inhibition when combined with PD-1 inhibitors." (PMID 41267084, 2025). "For instance, in pancreatic ductal adenocarcinoma, elevated levels of RIPK1, RIPK3, and MLKL are associated with accelerated tumor progression." (PMID 39949740, 2025). "Intratumor delivery of mRNA encoding necroptosis executor MLKL was shown to affect primary tumor growth as well as to protect against distal and disseminated tumor formations in mouse cancer models." (PMID 39737979, 2024). "In a B16-OVA tumor model and even a RIPK3-deficient CT26 tumor model, MLKL mRNA treatment induced necroptotic cell death and subsequent antitumor immunity." (PMID 38799433, 2024). "Anti-PD-1 therapy alone was barely responded in Hepa 1–6 tumors, while the treatment in MLKL-deficient tumors resulted in apparent tumor regression." (PMID 36650126, 2023). "In HCC cells with intrinsic RIPK3 deficiency, knockout of MLKL impedes the orthotopic tumor growth, activates the anti-tumor immune response and enhances the therapeutic effect of immune checkpoint blockade in syngeneic HCC tumor models." (PMID 36650126, 2023). "The results showed that PARP inhibition substantially restored the tumor growth of MLKL-KO tumors, which was associated with the reversed PAR polymer accumulation and CD8+ T cell infiltration." (PMID 36650126, 2023). "In great contrast to those implanted in the immune-competent mice, MLKL deficiency in HCC cells barely affected the tumor growth, suggesting the engagement of T cell response." (PMID 36650126, 2023). "We further asked how MLKL deficiency in cancer cells provokes anti-tumor immunity specifically in the hepatic tumor microenvironment." (PMID 36650126, 2023). "RIPK3 then phosphorylates mixed lineage kinase domain-like (MLKL), leading to plasma membrane disruption and release of DAMPs (damage-associated molecular patterns) and tumor antigens." (PMID 37513508, 2023). "For example, MLKL is linked to necroptosis in necrotic areas of solid tumors, an essential process that shapes the tumor microenvironment and promotes metastasis." (PMID 35422482, 2022). "Deficiency of either RIPK3 or MLKL prevented development of skin inflammatory lesion in RIPK1E-KO mice." (PMID 36344541, 2022). "Invasive tumors revealed lower expression of RIP3K and MLKL compared to non-invasive tumors, also the attenuated level of MLKL was associated with the tumor size in invasive NFPA." (PMID 34983494, 2022). "MLKL activation, on the other hand, is linked to highly aggressive tumor behavior and an immunosuppressive microenvironment." (PMID 36601479, 2022). "A previous study demonstrated that MLKL deficiency protected against necroptosis in cells including tumor cells, macrophages, and fibroblasts." (PMID 34194608, 2021). "Deficiency of MLKL prevents necroptosis in multiple cell types, including tumor cells, macrophages, and fibroblasts." (PMID 33937236, 2021). "In contrast RIPK1, RIPK3, and MLKL are widely expressed in human pancreatic ductal adenocarcinoma associated with robust manifestation of chemokines resulting in tumor promotion." (PMID 33567618, 2021).
tumor (continued). "An interesting study published more recently has evidenced that intra-tumor delivery of MLKL-encoding mRNA elicited a potent anti-tumor immunity, even if tumors were defective for proteins that acted upstream of MLKL." (PMID 32340261, 2020). "Recent studies have shown that chemotherapy normally killed RIP3 and MLKL-deficient tumor cells resulting in apoptosis by activating caspase-3 and yet was unable to reduce their growth in vivo." (PMID 31739592, 2019). "Necroptosis associated tumor repopulation after radiotherapy depended on activation of RIP1/RIP3/MLKL/JNK/IL-8 pathway." (PMID 31706322, 2019). "A potential way to restore these aberrations in the necroptotic pathway is by delivery of the executioner protein MLKL, e.g., encoded by in vitro transcribed mRNA, to the tumor cells." (PMID 31480289, 2019). "As for the clinicopathological characteristics, our analysis revealed that decreased expression level of MLKL was significantly associated with advanced tumor stage, more lymph node metastasis and older age." (PMID 30005626, 2018). "Mechanisms underlying the regulatory role of MLKL in tumorigenesis and tumor progression have been extensively investigated." (PMID 30005626, 2018). "The data above show that the antitumor response induced by intratumor treatment with mRNA encoding MLKL can lead to priming of tumor xeno-antigen-specific CD8+ and CD4+ T cells and to the elimination of cells that display this antigen." (PMID 30143632, 2018). "We demonstrate that intratumor administration of mRNA encoding MLKL elicits a potent antitumor T cell response—involving T cells directed against tumor neo-antigens—even in tumors that are defective for upstream necroptotic signaling proteins." (PMID 30143632, 2018). "Therefore, MLKL deficiency in HCC cells suppresses orthotopic tumor growth, activates the anti-tumor immune response, and enhances the therapeutic effect of immune checkpoint blockade in syngeneic HCC tumor mouse models." (PMID 38799433, 2024). "Moreover, high Skp2 mRNA or low MLKL mRNA expression in NSCLC tumor tissues was associated with worse overall survival (OS) by an online tool analysis." (PMID 37532777, 2023). "For example, necroptosis-induced CCL2 release depends on the activation of the receptor interaction protein 1 (RIP1)/RIP3/mixed lineage kinase-like (MLKL) pseudokinase, which may promote the oncogenic phenotype of tumor-associated astrocyte TAA.LncRNA." (PMID 35854199, 2023). "MLKL expression level in tumor tissues was significantly associated with the patient survival." (PMID 36650126, 2023). "We next treated MLKL-proficient and -deficient tumor-bearing mice with anti-PD-1 antibody." (PMID 36650126, 2023). "Tumor progression and reduced survival in patients with early-stage pancreatic adenocarcinoma, gastric, ovarian, and cervical squamous cancer is associated to low MLKL expression." (PMID 33567618, 2021). "In conclusion, this is the first study in human cancer patients to systematically analyze and compare the associations of MLKL and necroptosis activation with tumor-infiltrating immune cells in the tissue CCA microenvironment and their impact on clinical outcomes of the patients themselves." (PMID 34083572, 2021). "Furthermore, necroptosis-associated effector proteins RIPK1, RIPK3 and MLKL, identified in the Clinical Proteomic Tumor Analysis Consortium (CPTAC) validation cohort, were all up-regulated in the tumors, in line with our transcriptomic findings." (PMID 33672863, 2021). "Furthermore, reduced expression of MLKL has been reported to be associated with tumor metastasis into the lymph nodes." (PMID 33348858, 2020). "Therefore, we propose a novel pathway RIP1/RIP3/MLKL/JNK/IL-8 implicated in the necroptotic cells mediated tumor repopulation." (PMID 31706322, 2019). "We hypothesized that the induction of cell death in the tumor by mRNA encoding MLKL could promote the induction of antitumor T cell responses through the release of tumor antigens alongside DAMP12,41." (PMID 30143632, 2018).
tumor (continued). "In addition, our analysis revealed that decreased expression level of MLKL was significantly associated with advanced tumor stage, more lymph node metastasis and older age." (PMID 30005626, 2018). "mRNA encoding MLKL induced cell death with hallmarks of necroptosis in a variety of tumor cells." (PMID 31225452, 2018). "We opted to deliver the MLKL encoding mRNA by intra-tumor injection followed by electroporation." (PMID 31225452, 2018). "In summary, intratumor delivery of mRNA encoding MLKL elicits a strong and systemic antitumor immune response that reduces growth not only of the treated tumor but also can prevent secondary local and experimentally disseminated tumor formation." (PMID 30143632, 2018). "To gain more insight into the immune pathways responsible for the MLKL-mRNA-mediated antitumor responses, we probed the influx of DCs in the tumor bed and in the tumor draining lymph node by flow cytometry on days 1 and 2, respectively, after two intratumor treatments with mRNA encoding MLKL." (PMID 30143632, 2018). "However, the loss of kinase activity in RIPK3 or the loss of MLKL only marginally altered the ability of tumor cells to form in the lung." (PMID 28151480, 2017). "Therefore, in the envisioned strategy, Adriouch team aims to use viral vectors, akin to AAV, to induce ICD intratumorally by expressing active truncated/mutated forms of GSDMD, GSDME or MLKL, thus bypassing tumor resistance to the induction of pyroptosis or necroptosis." (PMID 35883457, 2022). "Taken together, these data suggest that for some tumors intrinsic defects in MLKL can result in tumor resistance to ICI immunotherapy with anti-PD-1 and/or anti-CTLA-4." (PMID 40345706, 2025). "Our findings that ICI immunotherapy relies on tumor cell-intrinsic RIPK3/MLKL signaling are in line with previous reports demonstrating that artificial activation of the necroptosis pathway can boost ICI antitumor efficacy." (PMID 40345706, 2025). "A meta-analysis of 613 cancer patients has demonstrated that decreased MLKL expression is correlated with advanced tumor stage and increased lymph node metastasis." (PMID 40691738, 2025). "Once activated and expanded—presumably in lymph nodes draining tumors with active MLKL-mediated necroptosis—CD8+ T cells are readily able to kill MLKL−/− tumor cells." (PMID 40345706, 2025). "The protective effect provided by MLKL is manifested in enhancing the antibacterial response and tumor suppression." (PMID 40788062, 2025). "MLKL-mRNA treatment rapidly induces T cell responses directed against tumor neoantigens, and requires both CD4+ and CD8+ T cells to prevent tumor growth." (PMID 41303584, 2025). "Of note, the indicated genetic deficiencies were only present in tumor cells while tumor-infiltrating immune or stroma cells in the TME were proficient for RIPK3 and MLKL in these experiments." (PMID 40345706, 2025). "The RIPK1/RIPK3/MLKL signaling cascade constitutes a central axis governing necroptotic cell death in tumor biology." (PMID 41180485, 2025). "We found evidence of superior disease control associated with prolonged progression-free survival in patients with high MLKL expression in pretreatment tumor samples." (PMID 40345706, 2025). "In line with that, ICI-induced accumulation of tumor antigen-specific CD8+ T cells in the TME was strongly reduced in MLKL-defective tumors." (PMID 40345706, 2025). "Accordingly, the increased metastatic incidence and multiplicity of primary tumor nodule formation in RPC mice was almost completely reversed upon functional inactivation of MLKL." (PMID 41413044, 2025). "Taken together, these data show that defective MLKL function in tumor cells resulted in reduced tumor antigen cross-presentation by cDC1s and suboptimal expansion and cytolytic function of tumor-infiltrating T cells upon ICI therapy." (PMID 40345706, 2025). "Its deletion leads to a reduction of more than 50% in tumor necrotic area and a significant decrease in MLKL phosphorylation." (PMID 41267084, 2025).